CCR7 (C-C motif chemokine receptor 7)
Diseases named in the same sentence as CCR7 in open-access papers (continued):
Sharing a sentence is not in itself a finding about the gene and the disease.
B cell lymphoma (8 papers, 2012 to 2022). "In a later study, the same group used the Eμ-Myc transgenic mouse model in which the B-cell lymphoma traffics to the lymph nodes and spleen via activation of CCR7." (PMID 35203305, 2022). "Each chemokine was tested for its ability to chemoattract L1.2 mouse B cell lymphoma cells expressing the cognate mouse receptors Ccr6, Ccr7, and Ccr1, respectively, in the presence of increasing doses of DOPS or DOPC liposomes." (PMID 34038417, 2021). "In a recent study conducted with B cell lymphoma cells, inhibition of CCR7 endocytosis reverted repulsion to attraction in high CCL19 concentration gradients." (PMID 26824863, 2016). "Furthermore, within the spleen niche, B-cell lymphoma cells interacted with gp38+ fibroblastic reticular cells, releasing homeostatic chemokines in response to CCR7 activation by CCL19 or CCL21 released by local stromal cells." (PMID 35203305, 2022). "Using transgenic mouse model which displayed an aggressive B-cell lymphoma phenotype, LTβR signalling has been shown to collaborate with CCR7 signaling to maintain T-cell and B-cell localization within the lymphoid microenvironment hence contribution to lymphomagenesis." (PMID 25211095, 2014). "Our results support that anti-CCR7 therapy might be indicated for patients suffering of CCR7-positive B cell non-Hodgkin lymphoma and CLL." (PMID 24305507, 2013). "In contrast, CCR7, CXCR4 and CXCR5 staining was both cytoplasmic and membranous for all 29 peripheral B-cell lymphomas." (PMID 35203305, 2022). "Helios+ FoxP3+ T cells in A20 B cell lymphoma tumors largely lacked CCR7 expression." (PMID 22292042, 2012). "We observed altered gene expression in the hyperexpanded clone at relapse, including increase of CCR7, which might play a role in the emigration of malignant B cells from the brain to the CSF, and CD81, which has been identified as a novel immunotherapeutic target for B cell lymphomas." (PMID 36153593, 2022).
hepatocellular carcinoma (8 papers, 2013 to 2025). A malignant tumor that arises from hepatocytes. "CCR7 was found to be strongly associated with a better outcome in hepatocellular carcinoma patients." (PMID 38552222, 2024). "Therefore, our team hypothesized that targeted regulation of VEGF-C and CCR7 may become a novel therapeutic option for the prevention and treatment of brain metastasis via lymphatic route in patients with hepatocellular carcinoma in the future." (PMID 37307828, 2024). "When patients develop brain metastasis from hepatocellular carcinoma, do the levels of VEGF-C and CCR7 in cerebrospinal fluid also change and become our molecular indicators to detect brain metastasis?" (PMID 37307828, 2024). "This is the first study exploring the effect of CCR7 on TGF-β1-induced EMT and coincides with a recent report demonstrating crosstalk between CXCR4 and TGF-β-induced EMT in hepatocellular carcinoma." (PMID 26176983, 2015). "Additionally, Kaplan-Meier survival analysis was conducted to illustrate the prognostic value of CCR7 and SPP1 in both the training and testing hepatocellular carcinoma (HCC) patient cohorts." (PMID 39635536, 2024).
oral squamous cell carcinoma (8 papers, 2021 to 2025). "This study aimed to investigate the impact of CC chemokine receptor 7 (CCR7) on the recruitment and polarization of tumor-associated macrophages (TAMs) in oral squamous cell carcinoma (OSCC)." (PMID 35904690, 2022). "Further research is needed to confirm the regulatory mechanism between CCR7 and Dusp1 and their impact on the tumor microenvironment of oral squamous cell carcinoma." (PMID 38539232, 2024). "CCR7 gene knockout can significantly inhibit the growth of mouse oral squamous cell carcinoma by promoting the polarization of M2 macrophages." (PMID 38539232, 2024). "Similarly, oral squamous cell carcinoma expresses CCR7, and CCL21‐mediated signaling leads to lymphatic metastasis, correlating with poor prognosis." (PMID 40038879, 2025). "Studies have shown that CCR7, an important inflammatory factor, can promote the proliferation and metastasis of oral squamous cell carcinoma (OSCC), but its role in the tumor microenvironment (TME) remains unclear." (PMID 38539232, 2024). "More recently, TN-C has also been shown to favor an immune-suppressive tumor microenvironment in oral squamous cell carcinoma, through the induction of a CCR7 signaling in dendritic cells, thus promoting the recruitment of T regulatory cells and the expression of anti-inflammatory cytokines." (PMID 34054795, 2021). "For example, CCR7 and its ligand chemokine ligand 21 (CCL21) promote the EMT and up-regulate the stemness of oral squamous cell carcinoma by activating the JAK2/STAT3 signaling pathway." (PMID 35538537, 2022). "A CC chemokine receptor 7 (CCR7) and CCL21 are abundant in oral squamous cell carcinoma (OSCC) tissues, where they regulate EMT process and promote OSCC desiccation through activation of the JAK2/STAT3 signaling pathway." (PMID 34421979, 2021). "For example, in oral squamous cell carcinoma, the CCL21/CCR7 axis activates the JAK2/STAT3 signaling pathway to regulate the progression of EMT and promote the stemness of oral squamous cell carcinoma." (PMID 33788424, 2021).
tongue squamous cell carcinoma (8 papers, 2019 to 2025). A squamous cell carcinoma that arises from the tongue. "Study also found that miR-532-3p affects the malignant behaviors of tongue squamous cell carcinoma by targeting the downstream gene CCR7." (PMID 33536018, 2021). "Another study indicated that miR-532-3p could directly modulating CCR7 expression, following by exert antitumor effect in tongue squamous cell carcinoma." (PMID 32499818, 2020). "Additionally, UCA1 might function as an oncogene in tongue squamous cell carcinoma (TSCC) through regulating the miR‐138‐5p/ CC chemokine receptor (CCR7) axis, and the interaction between miR‐138‐5p and UCA1 or CCR7 has been identified." (PMID 33565716, 2021). "Using the tongue squamous cell carcinoma cell line, SCC4, CCR7 activation promoted a more aggressive phenotype, whereas CCR7 inhibition reduced cell migration and invasion without affecting cell growth or survival." (PMID 35203305, 2022). "It was reported in tongue SCC that the high immunohistochemical expression of vascular endothelial growth factor C (VEGF-C), vascular endothelial growth factor receptor 3 (VEGFR-3), CCR7 and semaphorin 3E (SEMA3E) are predictors of metastasis." (PMID 31011147, 2019).
coronary artery disease (7 papers, 2018 to 2025). "This combined approach of bioinformatics and experimental validation has allowed the identification of CCR7 and FOXO1 transcripts as miRNA-regulated, Oxstress intermediates of coronary arterial disease." (PMID 32178422, 2020). "Our findings demonstrate that a simple six-colour flow cytometry panel targeting CD45, CD3, CD4, CD57, CCR7, and CD45RA could provide robust discrimination among healthy donors and patients at different stages of coronary artery disease (iCAD vs. ASCAD)." (PMID 40508061, 2025). "Levels of anti-HCMV IgG also positively correlated with both the percentage and absolute number of terminally differentiated CD8+ and CD4+ CD45RA+ CCR7- TEMRA cells, indicating that immunosenescence may participate in the development of coronary artery disease." (PMID 29988679, 2018). "CSF3, IL-1A, CCR7, IL-18, and MAPK14, as well as IL-17 signaling pathway and cytokine and cytokine receptor interaction signaling pathway related with inflammatory response might be the potential biomarker and targets for the treatment of coronary artery disease." (PMID 33777109, 2021).
diabetes (7 papers, 2008 to 2025). "CCR7−/− mice showed increased susceptibility to streptozotocin-induced diabetes and systemic autoimmune diseases, including SLE." (PMID 34220794, 2021). "The authors noted the failure of IL-21R deficient dendritic cells to acquire CCR7 which is needed for their migration to lymph nodes, may explain the reduction in the diabetes onset." (PMID 38720888, 2024). "The authors found that in a virus-induced diabetes model, DCs in the pancreatic draining lymph nodes of wild-type mice had high CCR7 expression, whereas IL-21R-/- mice showed significantly reduced CCR7 levels." (PMID 40376002, 2025). "The effect of diabetes on Ccr7 is consistent with a previous study showing reduced Ccr7 mRNA levels in lesional macrophages from regressing lesions in diabetic mice." (PMID 27351842, 2016). "Conversely, diabetes resulted in suppression of Ccr7 mRNA levels in macrophages through a non-EP4-dependent mechanism." (PMID 27351842, 2016). "In addition, diabetes exerted effects independent of myeloid cell EP4, including a reduction in macrophage Ccr7 levels and increased early atherogenesis characterized by relative lesional macrophage accumulation." (PMID 27351842, 2016).
Stroke (7 papers, 2016 to 2025). Sudden impairment of blood flow to a part of the brain due to occlusion or rupture of an artery to the brain. "Through single-cell RNA sequencing, we identified a novel GZMK+CD8+CD27+CCR7+ T-cell subset in patients with acute ischemic stroke (AIS), which we designated stroke-associated T (Tsa) cells." (PMID 40659887, 2025). "Similar results were recorded with the cylinder test, where animals injected with the CCR7 peptide 28–33 showed reduced bias on day 4 and 7 after PT stroke." (PMID 40659887, 2025). "Subsequent brain infiltration of Tsa cells is orchestrated by CCL19 derived from a specific endothelial cell subset after stroke via the CCL19/CCR7 axis." (PMID 40659887, 2025). "We identified a previously unrecognized GZMK+CD8+CD27+CCR7+ T-cell subset in AIS patients, named stroke-associated T (Tsa) cells, which was significantly positively correlated with the severity of clinical symptoms." (PMID 40659887, 2025). "Chemokines such as Cxcl5 and Ccr7 were also downregulated in both male and female stroke brains upon MMP-3 KO." (PMID 39000490, 2024). "Relative mRNA expression of CCR7 was significantly decreased in whole blood of stroke patients within 24 h of symptom onset compared to control (relative CCR7 expression = 0.4 ± 0.32, p = 0.03)." (PMID 26515089, 2016). "Genes related to inflammation such as Ccl5, Cxcl5, Il1a, Tnfsf10, Nfkb1, Tnfrsf1b, Ccr7, Tnfrsf9, Ccl7, Il1b, Il6, and Ccl24 were also downregulated upon MMP-3 KO in male stroke brains." (PMID 39000490, 2024). "Among them, VIM was positively correlated with the occurrence of stroke, while CARD11, ICAM2, CD19, and CCR7 were negatively correlated with the occurrence of stroke." (PMID 35722467, 2022). "The proportion of neutrophil distributed in the peripheral blood of stroke patients increased, in which the gene expression of IL7R, SLAMF1 and CCR7 were low, and vice versa." (PMID 32746852, 2020). "Human stroke genomic biomarker studies have identified a common panel of five genes responding to AIS in the peripheral blood: arginase 1 (ARG1), lymphocyte antigen 96 (LY96), matrix metalloproteinase 9 (MMP9), s100 calcium-binding protein A12 (s100A12), and chemokine CC motif receptor 7 (CCR7)." (PMID 26515089, 2016).
T-cell leukemia (7 papers, 2012 to 2022). A malignant disease of the T-lymphocytes in the bone marrow, thymus, and/or blood. "Overall, these data demonstrate that in addition to promoting metastasis to the lymph nodes, CCR7 also regulates metastasis of T-cell leukemia to the brain and central nervous system." (PMID 24259307, 2013). "Adult T-cell leukemia patients with lymphoid involvement were more likely to express CCR7 than patients with no lymphoid association." (PMID 35203305, 2022). "In addition, directing antibodies against CCR7 was highly effective in T-cell leukemia xenograft models." (PMID 33110606, 2020). "In addition, studies suggest that CCR7 mediates metastasis of T-cell leukemia to the central nervous system (CNS)." (PMID 24259307, 2013). "Interestingly, deletion of CCR7 in two models of B-cell leukemia failed to inhibit CNS infiltration, suggesting that CCR7 function may be specific for Notch1-induced T-cell leukemia." (PMID 28491865, 2017). "Adult T-cell leukemia cells were shown to be CD4+, CCR4+ and CD26− and patients who had aggressive disease were also CCR7 positive, whereas indolent patients were negative for both CCR7 and CD127 (interleukin 7 receptor α)." (PMID 35203305, 2022). "Although these cells lacked the capacity to seed the thymus, probably because they do not express CCR7 and CCR9, they underwent malignant transformation upon constitutive activation of Notch signaling and gave rise to T cell leukemia." (PMID 22355330, 2012). "Since the mAb did not recognize murine CCR7, we performed these studies in novel systemic xenogeneic models developed in host immunodeficient mice by intravenous injection of the SUP-T11 T-cell leukemia line, which, at the molecular level, resembles T-PLL as close as possible." (PMID 33110606, 2020).
thyroid cancer (7 papers, 2010 to 2024). "CCR7 expression has been shown to be lower in poorly differentiated compared with differentiated thyroid cancer which fits with more effector memory T cells (less CCR7) in advanced stages of thyroid cancer in our study." (PMID 38235146, 2023). "CCL21 is a ligand of the chemokine receptor CCR7, activation of which promotes thyroid carcinoma growth." (PMID 34522174, 2021). "CCR7, one of chemokine receptor involved in GPCR families, it is identified as tumor progression marker in thyroid cancer patients." (PMID 30420637, 2018).
tuberculosis (7 papers, 2011 to 2023). A chronic, recurrent infection caused by the bacterium Mycobacterium tuberculosis. "In the GSE20050, we found that when compared with normal lung parenchyma, LRRK2 was significantly down-regulated in caseous tuberculosis granulomas (p = 0.0361), but CCR7 and FYN was upregulated (p = 0.0024 and p = 0.0486, respectively)." (PMID 32987825, 2020). "NKG2A, NKG2C, NKG2D, CD16 and CCR7 molecules on γδ T cells were analyzed in 70 BD, 27 tuberculosis (TB) patients and 26 healthy controls (HC)." (PMID 23336215, 2013). "Expression of CD45RA, CCR7, and CD127 on M. tuberculosis-specific T cells secreting only IFN-γ or TNF-α was lowest in those with active tuberculosis." (PMID 23966657, 2013). "Thus, a combined cell surface loss of expression of CD45RA, CCR7, and CD127 on M. tuberculosis–specific CD4+ T cells is associated with both tuberculosis and recently acquired LTBI but not with remotely acquired LTBI." (PMID 28329119, 2017).
allergic asthma (6 papers, 2019 to 2023). A asthma with a basis in a pathological type I hypersensitivity reaction. "The mechanism underlying the role of CCR7-expressing DCs in the regulation of immune tolerance in the airways during allergic asthma remains unclear and requires further investigation." (PMID 31545493, 2019). "The present results suggested that the role of cytokines and IgE in immune inflammation and immune tolerance in allergic asthma may be associated with the expression level of CCR7 in DCs, suggesting that CCR7 may serve a role in DC-mediated immune tolerance in allergic asthma." (PMID 31545493, 2019). "They observed an elevation of GAB1 level in peripheral blood mononuclear cells from asthmatic patients during acute exacerbation, and further experiments found that GAB1 can regulate DC migration in allergic asthma by affecting CCL19/CCR7 signaling." (PMID 38057792, 2023). "The present study aimed to investigate the effects of CCR7 on DC-mediated immune tolerance in allergic asthma." (PMID 31545493, 2019). "Therefore, the present study investigated the effects of CCR7 knockdown and overexpression on DC-mediated immune tolerance in the lungs of rats with allergic asthma." (PMID 31545493, 2019). "Therefore, in the present study, the effects of CCR7 overexpression and knockdown in DCs on the mechanisms of immune tolerance were investigated in an animal model of allergic asthma." (PMID 31545493, 2019). "Moreover, further studies are required to examine the CCR7-dependent chemotaxis and CCR7-mediated signal transduction pathways, which may provide insights into novel therapeutic approaches for the treatment of patients with allergic asthma." (PMID 31545493, 2019). "Dendritic cells (DCs) have an important role in initiating and maintaining the immune inflammatory response in allergic asthma, and CC chemokine receptor 7 (CCR7) is directly involved in the pathogenesis of DC- and T cell-mediated allergic asthma." (PMID 31545493, 2019).
depression (6 papers, 2019 to 2025). "It has been demonstrated that the neuroprotective effects of CCR7 expression in astrocytes in inflammation during infection increased susceptibility to anxiety and depression in CCR7-knockout mice." (PMID 36561317, 2022). "It seems that the decreased expressions of CXCL1 and CCR7 will increase the risk of depression." (PMID 36561317, 2022). "The study found that the activation of the pro-inflammatory surface marker CCR7 is associated with depressive behavior, and that activation of CCR7 may aggravate anxiety and depression behavior in the male mice." (PMID 31341180, 2019). "We observed that genes connected with blood-brain barrier dysfunction, depressive disorders, and inflammation (CCR7, FOXF1) were enriched in SS relative to AA mice." (PMID 39629138, 2024). "Compared with the T2DM group, the expression level of CCR7 in the DD group was significantly upregulated (Fold change = 2.05), which may be related to the occurrence of depression." (PMID 31341180, 2019).
glioblastoma (6 papers, 2017 to 2025). The most malignant astrocytic tumor (WHO grade IV). "We provide important details to indicate that glioblastoma cell-secreted CCL21 plays a dual role both in recruiting plasmacytoid dendritic cells via binding to CCR7 and activating plasmacytoid dendritic cells through the CCR7/ACKR4—β-arrestin/CIITA pathway." (PMID 39456552, 2024). "Moreover, lymphatic endothelial-like cells are present in glioblastomas and promote the growth of CCR7-positive glioblastoma stem cells through CCL21-driven cholesterol metabolism." (PMID 40722703, 2025). "In addition, studies on glioblastoma have also reported that CCR7 activates TGF-β1-induced invasion, migration, and epithelial-mesenchymal transformation of human malignant gliomas by activating MMP2/9 and the nuclear factor KappaB signal transduction pathway." (PMID 35996545, 2022). "A recent study showed that lymphatic endothelial-like cells present in GBM could promote growth of CCR7-positive glioblastoma stem cells through CCL21 secretion." (PMID 39456552, 2024). "Within glioblastoma-infiltrating T cells, a large proportion of cells were positive for CXCR4 and the proportion of cells positive for chemokine receptors CCR4, CCR5, CCR6, CCR7, CXCR3, and CXCR6 ranged between 5-25%." (PMID 35464424, 2022).